IFITM3 (interferon induced transmembrane protein 3)
Diseases named in the same sentence as IFITM3 in open-access papers (continued):
Sharing a sentence is not in itself a finding about the gene and the disease.
tumor (continued). "To further assess the clinical relevance of IFITM3, we performed IHC analysis of tumor samples from 42 patients treated with chemotherapy and PD-1/PD-L1 inhibitors." (PMID 40611157, 2025). "In contrast, tumor-associated macrophage (TAM)-rich neighborhoods (C02) showed downregulation of IFN-α/β signaling genes (e.g., IFITM3, OAS1-3, MX1, ISG15), suggesting potential immunosuppression." (PMID 41138165, 2025). "In a tumor model, depletion of IFITM3 in regulatory T cells (Tregs) enhanced the translation and phosphorylation of STAT1." (PMID 40681213, 2025). "To determine the effects of IFITM3 alone and in combination with anti-PD-1, we conducted multiplex immune profiling of the tumor-infiltrating immune cell subsets." (PMID 40611157, 2025). "Compared with the control, IFITM3 overexpression significantly inhibited tumor growth, and the addition of anti-PD-1 further enhanced tumor suppression." (PMID 40611157, 2025). "Interferon-induced transmembrane protein 3 (IFITM3) acts as a surface marker for a diverse array of tumor stem cells, and research has demonstrated that the protein encoded by this gene is implicated in the progression of various malignancies." (PMID 41236096, 2025). "Through pseudotime analysis of tumor cells from scRNA-seq data, we identified molecular changes linked to differential MHC-I expression and established interferon-induced transmembrane protein 3 (IFITM3) as a key regulator of MHC-I in SCLC." (PMID 40611157, 2025). "IFITM3 plays a pivotal role in the regulation of various cellular biological processes, thereby significantly contributing to tumorigenesis and tumor progression." (PMID 41236096, 2025). "Results indicated that IFITM3 knockdown exhibited attenuated tumor growth and declined bFGF secretion." (PMID 38218875, 2024). "In cancer tissues, IFITM3 promotes tumor migration and invasion, promotes EMT through the Wnt/β-catenin signaling pathway, and its overexpression leads to poor prognosis." (PMID 38239300, 2024). "To clarify the mechanism underlying the reduced suppressive capacity of IFITM3-deficient Tregs, we isolated TI-Tregs from MC38 tumor-bearing WT and cKO mice for transcriptomic analysis." (PMID 38167862, 2024). "IFITM3, which is significantly overexpressed in cancer tissues, promotes tumor invasion and migration, and is also engaged in epithelial-mesenchymal transition (EMT) by the Wnt pathway (Rajapaksa, Jin & Dong, 2020)." (PMID 38239300, 2024). "As interferon-induced genes, STAT1 and IFITM3 were upregulated by IFNγ and other cytokines that induce Th1 response in the tumor microenvironment." (PMID 38167862, 2024). "Together, these findings suggested that IFITM3 in GBM stem cells would be responsible for increased angiogenesis in tumor microenvironment." (PMID 38218875, 2024). "Recent findings have indicated IFITM3 as a key role in a number of pathological process, particularly in neoplasms." (PMID 38218875, 2024). "IFITM1, IFITM2 and IFITM3 are induced by all types of interferon and are overexpressed in various tumor types, including CRC." (PMID 38962090, 2024). "To investigate the potential function of IFITM3 in the tumor microenvironment, we first explored the TCGA database to analyze the mRNA expression profile of IFITMs in different cancer types." (PMID 38167862, 2024). "To investigate the expression profile of IFITM3 in TI-Tregs, we next detected the IFITM3 expression in Treg cells isolated tumor tissue and corresponding normal tissue of COAD (n = 4) and ESCA (n = 6) patients." (PMID 38167862, 2024). "IFITM3 is known to regulate tumor occurrence and development by modulating cancer cell proliferation, cell cycle progression, and apoptosis." (PMID 39459876, 2024). "While the precise mechanisms and effects of IFITM3 in tumor immunity are not yet fully understood, its high expression in tumor cells suggests tumorigenic properties." (PMID 39459876, 2024).
tumor (continued). "Hypomethylated genes and promoters in this group seem to lose their tumor-suppressing effects (IFITM3 and GLIPR1L2) and perhaps show a reduction in oncogene activity (CAPS2)." (PMID 38791918, 2024). "We further performed ELISA to study the anti-tumor-specific response of IFITM3 cKO, STAT1 cKO, and double KO ex vivo by stimulating splenocytes against the MC38 cell line." (PMID 38167862, 2024). "Mechanistically, GSCs-derived IFITM3 causes activation of Jak2/STAT3 signaling and leads to robust secretion of bFGF into tumor environment, which eventually results in enhanced angiogenesis." (PMID 38218875, 2024). "IFITM3 in prostate cancer cells promotes tumor progression and bone metastasis by activating TGFβ pathways." (PMID 38218875, 2024). "And the results showed that IFITM3 was highly expressed in the fibroblasts, myofibroblasts, endothelial cells and tumor cells." (PMID 37304304, 2023). "Showed that IFITM3 is overexpression in HCC, and is associated with tumor invasion and proliferation in HCC." (PMID 37353775, 2023). "Studies have shown that IFITM3 plays a key role in tumor pathogenesis by regulating apoptosis, antiproliferative, and differentiation activities." (PMID 37602193, 2023). "A rising number of studies have found that IFITM3 is improperly expressed in a wide range of human malignancies and is likely involved in tumor progression." (PMID 37353775, 2023). "In tumor-infiltrating macrophages we also observed increased activation of cytokine-responsive genes IFITM3, CCR1 and UBB (FDR=10-4), as well as upregulation of genes involved in MHC Class II presentation H2-Aa, H2-Ab1, H2-Eb1 and CD74 (FDR=0.0015)." (PMID 36911698, 2023). "The expression of IFITM3 is positively correlated with Gleason score and T stage, and IFITM3 knockdown inhibits tumor cell migration and invasion; this inhibitory effect was more pronounced in transforming growth factor beta 1 (TGF-β1) pathway-activated cells." (PMID 37524814, 2023). "The signature genes positively correlated with IFITM3 are characteristic of tumor-promoting functions, including MYC targets." (PMID 35941699, 2022). "For instance, we examined the expression of Ifitm3 in our four single-cell tumor datasets and show that this gene is strongly expressed by all MYC subtypes." (PMID 35318328, 2022). "IFITM1 and IFITM3 are both overexpressed in most tumor tissues, whereas IFITM2 is overexpressed in only some tumor types and even downregulated in others." (PMID 36466909, 2022). "Overexpression of IFITM3 significantly augmented tumor growth of AGS xenografts in vivo, supporting the oncogenic property of IFITM3 in GC tumorigenicity." (PMID 35941699, 2022). "A pancancer analysis of transcriptomic data showed positive correlations between IFITM3 expression and immunomodulators (HLA, chemokines, and immunostimulators), tumor-infiltrating immune cells and immune checkpoints." (PMID 36466909, 2022). "According to previous studies, IFITM3 is an oncogene and promotes tumor progression in the majority of cancers but also exerts a tumor suppressive role in several cancers." (PMID 34456915, 2021). "IFITM3 was positively correlated with immunomodulators, tumor-infiltrating immune cells (TIICs), cancer immunity cycles, and inhibitory immune checkpoints." (PMID 34456915, 2021). "Taken together, these data suggest that IFITM3 is a pancancer classifier for high immunogenicity except for a few tumor types." (PMID 34456915, 2021). "Decrease the expression of miR-29a can reverse the expression of IFITM3 and promote the progress of tumor." (PMID 34659578, 2021). "Data in the Oncomine database indicated that levels of IFITM3 DNA copy number were significantly higher in tumor tissues than in normal tissues." (PMID 33816616, 2021). "Recently, increasing studies have reported that IFITM3 is abnormally expressed in various types of human cancers and that it participates in tumor development." (PMID 33816616, 2021).
tumor (continued). "In our validated cohort, we only assessed the expression of IFITM3 in cancer cells, and IFITM3 expression exhibited tight correlations with PD-L1 expression in tumor cells and the infiltration of CD8+ T cells." (PMID 34456915, 2021). "The expression of IFITM3 in BLCA found in public databases was inconsistent, but IFITM3 was highly expressed in the tumor tissues compared with paired paratumor tissues in the current cohort." (PMID 34456915, 2021). "We next performed a pancancer analysis to examine the immunological features of IFITM3 in all accessible tumor types in the TCGA database." (PMID 34456915, 2021). "In gastric carcinoma cell lines, knockdown of IFITM3 significantly suppresses tumor cell migration, invasion and proliferation in vitro." (PMID 33364194, 2020). "Direct overexpression of IFITM3 is associated with EMT, increased migration and invasion of tumor cells—yet a detailed mechanistic understanding for these phenotypes is still lacking." (PMID 33364194, 2020). "IFITM3 knock out tumor cells (IFITM3-/-) arrest at the G0/G1 phase and many cancer cell types display a reduced number of cells in the S phase." (PMID 33364194, 2020). "Curiously, IFNs possess anti-tumor activity, contrary to the phenotype driven by downstream IFITM3 expression." (PMID 33364194, 2020). "There is strong evidence from solid and hematological malignancies that IFITM3 itself has oncogenic properties and that these functions drive tumor progression." (PMID 33364194, 2020). "More research is needed to understand how IFITM3 expression changes in tumor and stromal cells as compared to normal cells, and how IFITM3 expression changes affect downstream signaling in these cells." (PMID 33364194, 2020). "Unpublished data from our lab demonstrates tumor spheres are readily formed in WT cells compared to IFITM3-/- cells." (PMID 33364194, 2020). "The expression of EMT relative protein E-Cadherin and N-Cadherin in cancer cells also changed after IFITM3 was silenced, indicating that the metastasis ability of tumor cells was reduced by inhibiting the EMT process." (PMID 31273201, 2019). "The result showed that IFITM3 knockdown significantly inhibited tumor cell migration and invasion, and this inhibitory effect was more pronounced in TGF-β pathway activated cells." (PMID 31273201, 2019). "Subsequently, we performed microarray analysis and found that IFITM3 participated in regulating tumor cell proliferation and metastasis via TGF-β-MAPK signaling pathway, which is consistent with most results obtained from KEGG and Gene Ontology analysis." (PMID 31273201, 2019). "In order to evaluate how irradiation and the related radio-induced upregulation of IFITM3 affects tumor formation, 100,000 rs1080 cells were intracranially implanted into the striatum of immunodeficient mice." (PMID 27835870, 2016). "As the diminished expression of IFITM3 has already been reported to have a critical role in tumor growth, a stable knock-down of IFITM3 in BTPCs has been achieved." (PMID 27835870, 2016). "Following these in vitro proliferation assays, the effect of enhanced IFITM3 expression on tumor growth was analyzed in mouse xenograft tumor models." (PMID 27835870, 2016). "Since IFN signaling affects many aspects of the immune system, we utilized a syngeneic tumor model in order to test the impact of ectopic IFITM3 expression in a functional immune environment." (PMID 27835870, 2016). "Regarding to the prognostic value of IFITM3, previous studies have elicited contradictory conclusions for different cancers, which reflects the complexity of IFITM3 in different tumor microenvironments." (PMID 26539332, 2015). "χ2 analysis demonstrated that the expression level of IFITM3 had a close relationship with T status of tumor (p = 0.015)." (PMID 26539332, 2015).
tumor (continued). "In this study, we first found the differential expression of IFITM3 in tumor tissues and their ANMs, as well as the important clinicopathological significance of IFITM3." (PMID 26539332, 2015). "Meanwhile, recent studies have also shown that IFITM3 plays a prominent role in tumor development and can be used as a tumor biomarker." (PMID 24370119, 2013). "IFITM1, IFITM2 and IFITM3 have miscellaneous functions including cell adhesion, antiproliferation, tumor suppression and embryonic development." (PMID 23166625, 2012). "IFITM1, IFITM2 and IFITM3 are involved in cell adhesion, antiproliferation, tumor suppression, and germ cell and embryonic development." (PMID 23166625, 2012). "Moreover, UMAP visualization confirmed that tumor cell clusters with high MHC-I expression exhibited concomitantly elevated IFITM3 levels." (PMID 40611157, 2025). "Notably, IFITM3 is frequently overexpressed in various tumor cells, correlating with the histopathological grading and staging of tumors." (PMID 40909948, 2025). "Furthermore, analysis of the Broad CCLE database revealed significantly lower IFITM3 expression in SCLC compared to tumor types characterized by higher MHC-I expression." (PMID 40611157, 2025). "Meanwhile, IFITM3 knockdown also inhibits migration, invasion, and proliferation of tumor cells." (PMID 41197719, 2025). "In addition, IFITM3 overexpression significantly increased CD3+ total T-cell infiltration within the tumor microenvironment." (PMID 40611157, 2025). "Therefore, IFITM3 would act as a hypoxia-induced intermediate factor in GSCs, and subsequently the affects the tumor microenvironment surrounding GSCs." (PMID 38218875, 2024). "In addition to its antiviral function, extensive research on IFITM3 has focused on its role in immune regulation, tumor development, and progression, and its effects on the nervous system." (PMID 39459876, 2024). "Furthermore, the overexpression of Ifitm2 and Ifitm3 within the tumor cell contributes to tumor progression and metastasis." (PMID 38919617, 2024). "And then S100A11 bound to IFITM3 and exerted the pro-tumour effect by activating Akt pathway." (PMID 39756316, 2024). "We found that IL12, IL27, and IFNγ, which could increase the STAT1 expression to induce Th1 response in the tumor microenvironment, could also induce high expression of IFITM3 of Treg cells." (PMID 38167862, 2024). "Similarly to our clinical data, Ifitm3 mRNA level was greatly increased in Treg cells from MC38 tumor tissue." (PMID 38167862, 2024). "Recent findings suggested IFITM3 as a key factor in tumor invasion and progression." (PMID 38218875, 2024). "In the mice tumor model, we observed that the deficiency of STAT1 or IFITM3 alone could induce fragile TI-Treg cells and thus strengthen anti-tumor immunity." (PMID 38167862, 2024). "Moreover, S100A11 binds to IFITM3, inducing Akt phosphorylation of living tumour cells after chemotherapy, which promotes tumour progression." (PMID 39756316, 2024). "Altogether, this study provides insights for clinical anti-tumor therapy and suggests that IFITM3 may emerge as an immune checkpoint on Treg cells." (PMID 38167862, 2024). "But whether and how IFITM3 acts to control Treg cell functions in anti-tumor immunity remains largely unexplored." (PMID 38167862, 2024). "Interestingly, it has been gradually unraveled that IFITM3 correlates with tumor progression, including proliferation, invasion, chemoresistance, metastasis, as well as angiogenesis." (PMID 38218875, 2024). "Besides elucidating the role of IFITM3 in Tregs, we also detected the IFITM3 expression in tumor-infiltrating CD4+ and CD8+ T cells to check its potential functions." (PMID 38167862, 2024). "Therefore, IFITM3 and the regulation of IFITM3-related protein complex can be targeted to minimize the Treg function in the tumor microenvironment." (PMID 38167862, 2024). "IFITM3 was highly expressed in GC tumors when compared to non-tumor counterparts." (PMID 35941699, 2022).
tumor (continued). "The correlation between IFITM3 expression and the inflammatory status in the tumor microenvironment might be beneficial for the identification of "hot" tumors." (PMID 36466909, 2022). "Therefore, IFITM3 expression is correlated with poor prognosis of PCa, as well as tumorigenesis, progression, differentiation, and tumor relapse." (PMID 36497496, 2022). "This review summarizes and discusses current knowledge of IFITM proteins, especially the immune-related proteins IFITM1, IFITM2 and IFITM3, different levels of regulation of their expression and function, and their involvement in immune processes and tumor transformation." (PMID 36466909, 2022). "In addition, by examining tumor tissue using qRT-PCR and western blotting, we found that the expression of IFITM3 in tumor tissues of mice with TUG1 knockdown was significantly lower than that in the other two groups." (PMID 34659578, 2021). "The purpose of the present study was to confirm the differential expression of TUG1 in HCC and to determine whether it regulates IFITM3 through miR-29a, thereby affecting tumor invasion, migration, proliferation, and apoptosis." (PMID 34659578, 2021). "Overall, IFITM3 might be a promising biomarker for identifying tumor immunogenicity and guiding immunotherapy." (PMID 34456915, 2021). "Theoretically, considering that IFITM3 is a crucial responder to inflammation to some extent, IFITM3 may play a significant role in regulating tumor immunity, but its role as an immunomodulator in human cancers has not been well defined." (PMID 34456915, 2021). "The expression of IFITM3 appears to promote tumor progression in HCC." (PMID 33816616, 2021). "The lung metastasis test showed that the degree of tumor metastasis and the average area of IFITM3 immune-positive lung tissue were significantly reduced after knocking down TUG1, whereas simultaneous knocking down TUG1 and miR-29a resulted in findings similar to those obtained in the control group." (PMID 34659578, 2021). "IFITM3 was enhanced in most tumor tissues in comparison with adjacent tissues." (PMID 34456915, 2021). "IFITM3 expression levels likely rise secondarily to IFN during tumor immune/inflammatory responses." (PMID 33364194, 2020). "As discussed here, IFITM3 has a multi-dimensional role and may join multiple signaling pathways that are responsible for oncogenesis and tumor progression." (PMID 33364194, 2020). "Blocking IFITM3 may lead to changes in downstream signaling and help abrogate tumor progression – an observation that has important implications for designing future cancer therapeutics." (PMID 33364194, 2020). "It seems reasonable to speculate that overexpression of IFITM3 is part of an anti-tumor immune/inflammatory response." (PMID 33364194, 2020). "Lastly, a recent paper shows IFITM3 is correlated with the inhibitory immune checkpoint receptors PD-L1, B7-H4, VISTA, IDO, and the tumor associated macrophage markers CD68, CD163, and CD206, which are associated with tumor immunosuppression." (PMID 33364194, 2020). "Indeed, transient overexpression increases tumor cell migration and invasion—supporting a role for IFITM3 in metastasis." (PMID 33364194, 2020). "Since IFITM3 acts a pivotal role in the malignant proliferation and metastasis of tumor cells, we examined the key molecules of common pathways such as cell cycle, proliferation, and metastasis by using the Western blotting method to explore the relevant mechanism of IFITM3." (PMID 31273201, 2019). "Likewise, the expressions of these protumor metastasis factors also underwent significant changes, further validating that IFITM3 promotes tumor metastasis." (PMID 31273201, 2019). "Therefore, we think the roles of IFITM3 in various cancers possibly depend on tumor growth microenvironment." (PMID 24370119, 2013).